VIM (vimentin)
Diseases named in the same sentence as VIM in open-access papers (continued):
Sharing a sentence is not in itself a finding about the gene and the disease.
lung squamous cell carcinoma (6 papers, 2012 to 2022). "Similarly, lung squamous cell carcinoma patients with expression of vimentin, a mesenchymal marker, have significantly reduced overall survival than patients whose tumors lack vimentin." (PMID 33673197, 2021). "Therefore, we selected SOX2, KRT5 and KRT14 stemness gene proteins, PD-L1 immune related proteins, vimentin protein, and EpCAM protein, all of which influence epithelial carcinogenesis, to explore whether the mechanism at the cell level corresponds to lung squamous cell carcinoma pathogenesis." (PMID 36056339, 2022). "In lung squamous cell carcinoma patients, EDIL3 expression was significantly correlated with low e-cadherin expression and high vimentin expression (P = 0.021 and P = 0.002, respectively)." (PMID 28819306, 2017).
metastatic prostate carcinoma (6 papers, 2011 to 2023). A carcinoma that arises from the prostate gland and has spread to other anatomic sites. "There is strong evidence to support a major role for vimentin in the regulation of cancer growth, showing a higher protein expression level in metastatic prostate cancer patients with a Docetaxel resistance, in the context of the EMT phenotype." (PMID 37108678, 2023). "In summary, this study revealed that EpCAM antibodies were more effective in isolating CTCs from patients with localized prostate cancer, while vimentin antibodies were superior for in metastatic prostate cancer." (PMID 37345161, 2023). "Interestingly, EpCAM antibodies were more effective for localized prostate cancer, while vimentin antibodies excelled in metastatic prostate cancer isolation." (PMID 37345161, 2023). "Accumulating data also suggest that both vimentin and nestin may be the key players in the transition from androgen-dependent to castration-resistant metastatic prostate cancer." (PMID 24086245, 2013).
multiple myeloma (6 papers, 2015 to 2025). "Specific immunohistochemical staining for HPSE and mesenchymal marker vimentin was performed on 35 newly diagnosed, treatment naïve myeloma patient bone marrow core biopsy specimens." (PMID 26849235, 2016). "We observed that vimentin inhibition significantly prevented HPSE-high myeloma cells from homing to and growing in bone." (PMID 26849235, 2016). "Similar to HPSE transfected cells (HPSE-high cells), the addition of rhHPSE resulted in significantly enhanced vimentin expression in both wild-type CAG and RPMI 8226 myeloma cell lines, however E-cadherin expression was only slightly decreased." (PMID 26849235, 2016). "These experiments demonstrated that inhibition of ERK signaling significantly inhibited HPSE (both transfected HPSE and rhHPSE) enhanced vimentin expression, suggesting the involvement of the ERK pathway in HPSE-enhanced mesenchymal phenotype in myeloma cells." (PMID 26849235, 2016). "In the present study, we demonstrate, through the analysis of multiple MM cell lines and primary myeloma cells from MM patients that myeloma cells do express a number of EMT markers (e.g., E-cadherin, Vimentin, Fibronectin, and RANK) and that the expression of these markers is regulated by HSPE." (PMID 26849235, 2016).
myxoma (6 papers, 2015 to 2025). A benign soft tissue neoplasm characterized by the presence of spindle and stellate cells, lobulated growth pattern, and myxoid stroma formation. "Myxomas show a diffuse positive reaction for the immunohistochemical marker Vimentin and focal expression of CD34, CD68, and SMA." (PMID 26509093, 2015). "All myxomas showed strong reactivity to vimentin confirming our diagnosis." (PMID 35778593, 2022). "On immunohistochemical staining, the spindled cells of myxomas stain positive for vimentin and negative for S100, cytokeratins, BCL2, Alk-1, and other neural and muscle markers." (PMID 41036027, 2025). "SCC typically stains positive for CK, P40, and P63, while adenocarcinoma exhibits positivity for CK, CK7, thyroid transcription factor 1, and napsin A. Myxoma tumour cells express calretinin, and markers such as actin, CD31, S-100, and vimentin are variably expressed." (PMID 39844903, 2024). "From the limited data we have and the observations of this study, primary myxomas were typical of mesenchymal origin with strong staining with vimentin and absent expression of the tumor cells to SMA." (PMID 35778593, 2022). "The myxoma cells revealed positive for vimentin and CD34, but negative for S-100 and α-SMA." (PMID 38457580, 2024).
nasal polyps (6 papers, 2017 to 2026). "Vimentin expression levels in untreated RECs were consistent with a previous study, which showed that healthy inferior turbinates have lower expression of vimentin than nasal polyps." (PMID 29940929, 2018). "Early-stage nasal polyps exhibit increased TGF-β1 levels and more epithelial loss and induced myofibroblast differentiation with activated α-SMA and vimentin." (PMID 28615628, 2017). "Moreover, S. aureus is involved in nasal polyposis pathogenesis; nasal polyps lack expression of E-cadherin and occluding, while TGFβ and vimentin are overexpressed compared with healthy nasal mucosa, indicating a role of S. aureus in EMT." (PMID 35740629, 2022). "Double immunofluorescent staining (Vimentin/ α-SMA or IL-25/ α-SMA) was conducted to investigate whether myofibroblasts (active form of fibroblast) were involved in pathogenesis of nasal polyp of the CRSwNP group." (PMID 28771607, 2017). "Specific biomarkers, such as E-cadherin and EpCAM for epithelial cells and vimentin and N-cadherin for mesenchymal cells, have been identified as markers of EMT activity within nasal polyps 5-8." (PMID 41583532, 2026). "We found that E-cadherin, vimentin, fibronectin, and α-SMA expression was increased in nasal polyps compared to inferior turbinates." (PMID 28804222, 2017). "Staining for the mesenchymal markers vimentin, α-SMA, and fibronectin in nasal polyps was strongly positive in submucosal tissues and weaker on the apical epithelial side." (PMID 28804222, 2017). "To investigate whether EMT occurs in CRS tissues in vivo, we examined the fluorescent immunocytochemical expression of the EMT markers including E-cadherin, vimentin, α-SMA, and fibronectin—in six nasal polyps and six normal inferior turbinates." (PMID 28804222, 2017). "During the development of nasal polyps, EMT leads to a shift from epithelial characteristics to mesenchymal traits, characterized by a decrease in epithelial markers (E-cadherin and EpCAM) and an increase in mesenchymal markers (vimentin, FBN, and N-cadherin) 5-8." (PMID 41583532, 2026).
neurofibroma (6 papers, 2004 to 2025). An intraneural or extraneural neoplasm arising from nerve tissues and neural sheaths. "Plexiform schwannoma is distinguished from plexiform neurofibroma by the presence of vimentin and myelin basic protein in addition to being strongly positive for the S100 protein." (PMID 19568560, 2009). "We further examined whether the mesenchymal marker vimentin and EMT-related collagens are also expressed in NF1-associated neurofibroma specimens." (PMID 29666462, 2018). "On immunohistochemistry the tumor was positive for S100, Neurofilament, vimentin, and negative for epithelial membrane antigen, in combination with the morphological features a diagnosis of neurofibroma was made." (PMID 15363097, 2004).
Parkinson disease (6 papers, 2011 to 2025). A progressive degenerative disorder of the central nervous system characterized by loss of dopamine producing neurons in the substantia nigra and the presence of Lewy bodies in the substantia nigra and locus coeruleus. "Ashwagandha; SH-SY5Y; 6-Hydroxydopamine; Parkinson's disease; Neuroprotection; Peroxidase activity; Thioltransferase activity; Peroxiredoxin; Vimentin; VGF; Protein glutathionylation." (PMID 34765761, 2021). "Vimentin is the biomarker of several brain diseases with increased expression in rat models for Alzheimer's and Parkinson's disease." (PMID 34765761, 2021). "To determine the role of KSM-66 in neuroprotection, we studied possible changes in peroxiredoxin I, VGF and vimentin expression by analyzing lysates of 6-OHDA treated SH-SY5Y cells as a model of Parkinson with pre/post treatment with 0.5 mg/ml KSM-66 for 24 h." (PMID 34765761, 2021). "The reduced mitochondrial potential in vimentin-null cells may parallel the mitochondrial impairments seen in conditions like Parkinson’s disease or amyotrophic lateral sclerosis (ALS), where mitochondrial bioenergetics are often compromised." (PMID 39765662, 2024). "Previously several oxidative stress proteins were differentially expressed in SH-SY5Y cells, Parkinson's model cells, treated with 6-OHDA e.g. vimentin, peroxiredoxin." (PMID 34765761, 2021).
Peritoneal Fibrosis (6 papers, 2018 to 2023). Disorder characterized by a wide range of structural changes in PERITONEUM, resulting from fibrogenic or inflammatory processes. "Additionally, a deficiency in the eNOS signaling pathway could exacerbate peritoneal fibrosis in mice by increasing the expression of vimentin." (PMID 35620579, 2022). "The protective effects of ONO-AE3-208 on peritoneal fibrosis were further demonstrated by its ability to inhibit FN, collagen I, and vimentin at both the mRNA and protein levels." (PMID 36438844, 2022). "Moreover, elevated expression levels of Vimentin along with down-regulated ZO-1 mRNA and protein expression in patients with peritoneal fibrosis." (PMID 35383161, 2022).
schizophrenia (6 papers, 2011 to 2021). A major psychotic disorder characterized by abnormalities in the perception or expression of reality. "Age of onset negatively correlated with CD14, IL6R, IL1R1, SERPINA3, pan-GFAP and VIM mRNAs in schizophrenia and CD14, IL1B, SERPINA3, pan-GFAP and VIM mRNAs in bipolar disorder." (PMID 34911938, 2021). "There were 5 intermediate filament proteins with disturbed abundance in schizophrenia: desmin (DES), vimentin (VIM), glial fibrillary acidic protein (GFAP), and neurofilament medium and light chains (NEFM and NEFL)." (PMID 26909022, 2016).
scleroderma (6 papers, 2012 to 2025). Scleroderma is a rare autoimmune connective tissue disorder characterized by abnormal hardening of the skin and, sometimes, other organs. "EchA treatment reduces the number of activated myofibroblasts expressing α-SMA, vimentin, and phosphorylated Smad3 in bleomycin-induced scleroderma." (PMID 33922418, 2021). "Activated fibroblasts or myofibroblasts, characterized by an increased expression of α-smooth muscle actin (α-SMA) and vimentin, are the key effector cells in scleroderma." (PMID 33922418, 2021). "WKYMVm-treated scleroderma skin tissues displayed reduced numbers of myofibroblasts expressing α-smooth muscle actin, Vimentin, and phosphorylated SMAD3." (PMID 31552041, 2019). "Activated fibroblasts or myofibroblasts, characterized by increased expression of α-smooth muscle actin (α-SMA) and Vimentin, are the key effector cells in scleroderma." (PMID 31552041, 2019). "Besides, α‐smooth muscle actin (αSMA), Fibulin 1 (FBN1), and vimentin (VIM) which are often used to identify pathologic fibroblasts and myofibroblasts were highly expressed in the dermis of scleroderma skin, compared to the control group." (PMID 35315234, 2022). "Pathological stainings also showed that the expressions of fibrotic markers (α‐SMA, VIM, and EN1) were significantly downregulated in the skin tissues of scleroderma mice after EM organoid treatment." (PMID 35315234, 2022). "The number of Vimentin+p-SMAD3+ myofibroblasts increased in the BLM-induced scleroderma model, and WKYMVm treatment markedly reduced the BLM-induced increase of Vimentin+p-SMAD3+ cell number." (PMID 31552041, 2019). "In our study, WKYMVm treatment led to decreased production of myofibroblasts positive for α-SMA, Vimentin, and phospho-SMAD3 through an Fpr2-dependent mechanism in the scleroderma model." (PMID 31552041, 2019). "To explore the effects of WKYMVm on myofibroblast differentiation, we performed immunostaining of the scleroderma skin specimens with antibodies against α-SMA and Vimentin, which are markers for myofibroblasts." (PMID 31552041, 2019). "Similar results were obtained in scleroderma fibroblasts (SCL), rat cardiac fibroblasts (RCF) and mouse embryonic fibroblasts (MEFs) suggesting that WF-A can disrupt vimentin filaments in fibroblasts of different sources." (PMID 22900077, 2012). "Furthermore, WKYMVm treatment did not reduce the numbers of Vimentin+ or Vimentin+p-SMAD3+ myofibroblasts in the scleroderma skin of Fpr2 KO mice, in contrast to the significant inhibition of those in the scleroderma skin of wild type mice." (PMID 31552041, 2019).
small cell lung carcinoma (6 papers, 2018 to 2025). Small cell lung cancer (SCLC) is a highly aggressive malignant neoplasm, accounting for 10-15% of lung cancer cases, characterized byrapid growth, and early metastasis. "Phosphorylation proteomics data reveal that in FAT1-mutated small cell lung cancer, 24 phosphorylation sites of VIM exhibit significant increases." (PMID 41153737, 2025). "These sites are primarily involved in cytoskeletal recombination and cell motility processes, indicating a close relationship between VIM phosphorylation and the metastatic potential of small cell lung cancer." (PMID 41153737, 2025). "Vimentin is widely used to detect mesenchymal-like CTCs in aggressive cancer subtypes such as small cell lung cancer (SCLC), advanced NSCLC, and poorly differentiated pancreatic cancer." (PMID 39671082, 2024). "Loss of CREBBP has been shown to reduce histone acetylation and transcription of cellular adhesion genes in small cell lung cancer, whereas MUC16, which is related to many types of cancers, increases metastasis via modulation of E‐cadherin, N‐cadherin, and vimentin expression." (PMID 38323355, 2024).
thyroid tumor (6 papers, 2014 to 2025). A benign or malignant neoplasm affecting the thyroid gland. "A significant increase in the number of vimentin-positive cells was observed in thyroid tumors from 2-, 4- and 8-month-old RET/PTC3 Dicer1(+/+) mice compared to WT thyroids, which was expected given the tumoral context." (PMID 41002430, 2025). "Vimentin-positive cells represented up to 40% of the thyroid tumor cell population." (PMID 41002430, 2025). "The low-grade hyaline-type cartilage in the left thyroid tumor was positive for vimentin." (PMID 32693811, 2020). "The positive rate of expression of vimentin in both the thyroid tumors was 90%." (PMID 32693811, 2020). "A significant loss of E-cadherin gene expression and an increase in vimentin gene expression was seen in the BRAFV600E thyroid tumors compared to normal thyroid and similar data were obtained by immunohistochemistry where vimentin staining was highly positive only in BRAFV600E tumor specimens." (PMID 25076938, 2014). "Immunolabelings against cytokeratin-8 (CK8), vimentin and alpha-smooth muscle actin (α-SMA) were conducted to study the cellular composition of thyroid tumors." (PMID 41002430, 2025).
tuberculosis (6 papers, 2017 to 2022). A chronic, recurrent infection caused by the bacterium Mycobacterium tuberculosis. "Vimentin also has an antigenic function in tuberculosis and is overexpressed in macrophages infected by Mycobacterium tuberculosis, which are subsequentially targeted for killing." (PMID 35336202, 2022). "A crucial finding is that vimentin did not elicit a pro-inflammatory cytokine response in PBMCs from tuberculosis patients, despite the substantial accumulation of vimentin within tuberculosis granulomas." (PMID 28114394, 2017). "Although we used a Kv and vimentin concentration similar to that used for PPD stimulation of tuberculosis PBMCs in our previous work, we did not perform a dose response curve at different concentrations." (PMID 28114394, 2017).
type 2 diabetes (6 papers, 2018 to 2025). "Positive co-staining with glucagon and vimentin has been reported in isolated case reports in biopsies from patients with chronic pancreatitis and type 2 diabetes." (PMID 39836539, 2025). "Electron microscopy with immunogold staining demonstrated the presence of vimentin in intermediate filament bundles within the cytoplasm of α-cells in type 2 diabetes." (PMID 39836539, 2025). "VIM expression in islet cells is higher in type 2 diabetes, although VIM protein levels were lower in placenta from obese pregnant women with normal glucose tolerance." (PMID 31110514, 2019). "Low levels of glucagon and vimentin co-expression, and even lower insulin-vimentin co-expression, have been recently reported in normal human pancreas while a higher co-expression was found in type 2 diabetes." (PMID 29360826, 2018).
acute myeloid leukemia (5 papers, 2018 to 2023). Acute myeloid leukemia (AML) is a group of neoplasms arising from precursor cells committed to the myeloid cell-line differentiation. "In acute myeloid leukemia (AML), the direct co-culture of AML tumor cells and mesenchymal/fibroblastic HS5 cells results in the upregulation of the vimentin level—a main EMT pathway—and increases the metastatic phenotype of AML cells." (PMID 38002286, 2023).
amyloid (5 papers, 2014 to 2023). "Morphologically, reactive astrocytes hypertrophy, increase expression of cytoskeletal proteins such as GFAP and vimentin, and are found surrounding amyloid plaques where their processes extended into the plaque core." (PMID 37533101, 2023). "While the exact function of reactive astrocytes is still not fully understood, genetic deletion of Gfap and Vimentin increased plaque load in APP/PS1 mice, suggesting that acquiring a reactive phenotype supports astrocytes in limiting amyloid pathology." (PMID 32197653, 2020). "Attenuation of astrocytic activation via deletion of GFAP and vimentin in APP/PS1 mice exacerbated amyloid plaque load independent of APP processing and Aβ production, suggesting that astrocytes are important in amyloid clearance." (PMID 24490742, 2014). "We found a reduction in the numbers of Nestin-, Vimentin-, Nestin/Vimentin-, and Sox 2-positive cells in the olfactory bulb, hippocampus, and SVZ after amyloid exposure, although in some cases, the reduction was not significant." (PMID 36499771, 2022).
anaplastic thyroid carcinoma (5 papers, 2021 to 2026). "A previous report from Li revealed that EGCG suppressed epithelial–mesenchymal transition and migration by blocking TGF-β/Smad-signaling pathways and downregulation of Vimentin in anaplastic-thyroid-carcinoma (ATC) 8505 C cells." (PMID 33747527, 2021). "Notably, rhabdomyosarcomatous differentiation of anaplastic thyroid carcinoma is characterized by weak staining for epithelial markers and strong staining for vimentin, actin, desmin, and myoglobin." (PMID 39420880, 2024). "Immunohistochemical (IHC) analysis showed that the anaplastic thyroid carcinoma expressed vimentin, while it lacked the expression of CK, CK19, and thyroglobulin." (PMID 41124647, 2026).
cervical squamous cell carcinoma (5 papers, 2016 to 2025). A squamous cell carcinoma arising from the cervical epithelium. "At the clinical level, we collected cervical biopsy specimens from HPV-positive patients and verified the expression patterns of PGRMC1 and VIM using immunohistochemical staining in cervical squamous cell carcinoma (CSCC) tissues." (PMID 41153737, 2025). "NR5A2 and the key gene vimentin (VIM) were significantly co-expressed in cervical squamous cell carcinoma, and VIM was also significantly co-expressed with EMT signaling pathway genes." (PMID 36232920, 2022). "Interestingly, a study based on cervical squamous cell carcinoma showed that upregulation of vimentin was inversely related to histologic differentiation, metastasis, and recurrence." (PMID 27190522, 2016).